TNS3 (tensin 3)
Diseases named in the same sentence as TNS3 in open-access papers (continued):
Sharing a sentence is not in itself a finding about the gene and the disease.
cancer (continued). "The positive correlations of TNS3 and MKI67 were found in most cancers, including ESCC." (PMID 34047714, 2021). "It is known that c-Src promotes cancer proliferation by activating Ras/Raf/ERK1/2 and PI3K/AKT signaling pathways, suggesting that the oncogenic role of TNS3 in ESCC could be involved in these pathways." (PMID 34047714, 2021). "Several proteins involved in cytoskeleton rearrangement such as actin, TNS3, KIF23, CKAP2L, NEDD9 and PLEC were also hyperphosphorylated, indicating the known regulatory role of AXL in promoting cancer cell migration/invasion and inducing epithelial-mesenchymal transition (EMT)." (PMID 34439388, 2021).
tumor (17 papers, 2016 to 2025). "In RCC, comparative analysis of 223 tumors and 48 normal kidney cortex tissues revealed significantly reduced TNS3 mRNA in tumor samples, where a higher tumor grade correlated with lower expression." (PMID 40906372, 2025). "The most striking feature of tensins, particularly TNS1 and TNS3, is their context-dependent duality, acting as either oncoproteins or tumor suppressors in different malignancies or even different subtypes of the same malignancy." (PMID 40906372, 2025). "Critically, using multiple datasets, we observe a positive correlation between ETS1 and TNS3 RNA levels in EWS tumor samples, suggesting that EWS tumor cells expressing ETS1 have the potential to exhibit a phenotype that promotes cell movement." (PMID 38187702, 2023). "The intracellular localization of TNS3 has been shown in tumor cells, but had yet to be determined in BMSCs." (PMID 37668682, 2023). "A microscopic analysis demonstrated that positive expression of TNS1, TNS2 and TNS3 proteins in tumor cells was present in 7 (7.78%), 4 (4.44%) and 32 (35.56%) out of 90 patients, respectively." (PMID 33926026, 2021). "We noted that the positive expression of TNS1 and TNS2 was not common in tumor cells, whereas the positive expression of TNS3 occurred in tumor cells of about one-third of GC patients." (PMID 33926026, 2021). "We observed a significant increase of TNS3 expression in tumor blocks as compared to the normal blocks." (PMID 34047714, 2021). "We further investigated the role of TNS3 in vivo using subcutaneously xenograft tumor mice model and found that KYSE150 expressing shTNS3 (#2) significantly reduced the tumor volume and weight compared to shNC." (PMID 34047714, 2021). "In vivo xenograft model confirmed that the ratio of MSI1/TNS3 expression is important for GBM tumor migration." (PMID 28821879, 2017). "We also confirmed that MSI1 and TNS3 expressions are mutually exclusive in migratory tumor lesions, and GBM patients with MSI1high/TNS3low pattern tend to have poor clinical outcome." (PMID 28821879, 2017). "TNS3 was found positively correlated with the tumor malignancy and poor prognosis in the patients." (PMID 34047714, 2021). "Together, these data showed that the TNS3 short form has a function distinct from that of canonical TNS3, and may drive tumor initiation or progression." (PMID 34811492, 2021). "These suggested TNS3 acts as a tumor suppressor in multiple cancers." (PMID 33824309, 2021). "We also detected decreased expressions of TNS3 and Ki-67 in subcutaneous tumor blocks (shTNS3 #2)." (PMID 34047714, 2021). "Although previous studies have demonstrated the tumor suppressor role of TNS3 in untransformed MCF10A and standard HEK293; the opposing role could be due to DLC1 binding to its SH2 domain in the case of lower Src activity." (PMID 34047714, 2021). "In a xenograft animal model, high expression ratio of MSI1 to TNS3 enhanced GBM tumor migration." (PMID 28821879, 2017). "Consequently, mutations in EGFR or Src across different cellular contexts may differentially redirect TNS3’s functional impact on tumor progression." (PMID 40906372, 2025). "It targets TNS3 and PXN in macrophages, while also regulating CCL2 expression in tumor cells, creating a supportive niche for tumor progression." (PMID 40647470, 2025). "In tumor cells of all cases, we observed both membranous and cytoplasmic expressions of TNS1, TNS2, and TNS3 proteins." (PMID 33926026, 2021). "Collectively, these data suggest that tumor-derived miR-375 increased MΦ migration by downregulating the migration inhibitory proteins PXN and TNS3 in MΦ." (PMID 30850595, 2019). "In macrophages, miR-375 directly targets TNS3 and PXN to enhance macrophage migration and infiltration into tumor spheroids and in tumors of a xenograft mouse model." (PMID 30850595, 2019). "An analysis of 46 paired tumor/non-cancerous tissues identified significant TNS3-203 transcript overexpression in malignant tissues." (PMID 40906372, 2025).
tumor (continued). "Importantly, interrogation of tumor gene expression profiles from five independent datasets showed a positive correlation of ETS1 and TNS3 expression and association of high TNS3 expression with a poorer overall survival probability." (PMID 38187702, 2023). "Subsequently in vitro and in vivo assays revealed the pro-proliferative role of TNS3 in ESCC, inhibition of which could increase the sensitivity of tumor cells to LMK-235 treatment." (PMID 34047714, 2021). "We provide information that tumor-derived miR-375 alters MΦ infiltration and migration by targeting TNS3 and PXN mRNA expression, without affecting polarization." (PMID 30850595, 2019). "In addition, we found that TNS3 plays a pro-proliferative role in ESCC both in vitro and in vivo, which if inhibited could enhance the sensitivity of the tumor cells to LMK-235." (PMID 34047714, 2021). "MiR-375 is released from apoptotic tumor cells as LDL binds a nonexosomal entity that is absorbed by TAMs via CD36, which alters the expression of Tensin 3 (TNS3) and PXN, two genes involved in the migration and infiltration of macrophages." (PMID 36189271, 2022).
TNS3 also shares sentences with these, for which no sentence is quoted: infection (2 papers); non-small cell lung carcinoma (2); pancreatic cancer (2); acute myeloid leukemia (1); Allergy (1); brain injury (1); Ewing sarcoma (1); infertile (1); liver cancer (1); lung adenocarcinoma (1); lung squamous cell carcinoma (1); memory impairment (1); metastatic melanoma (1); osteosarcoma (1); prostate adenocarcinoma (1); thyroid (1).